HOXA13 (homeobox A13)
Description:
Sequence-specific, AT-rich binding transcription factor which is part of a developmental regulatory system that provides cells with specific positional identities on the anterior-posterior axis. Sequence-specific transcription factor which is part of a developmental regulatory system that provides cells with specific positional identities on the anterior-posterior axis.
Synonyms: HOX1J; HOX1
Tractability: PROTAC: ubiquitination databases record sites on it.
Gene: Protein-coding gene on chromosome 7 (27,193,503 to 27,200,091, reverse strand). Ensembl gene ENSG00000106031.
Subcellular location: Nucleus
Subcellular location (Human Protein Atlas): Nucleoplasm; Intermediate filaments; Mitotic chromosome
Gene Ontology:
Molecular function: sequence-specific DNA binding; sequence-specific double-stranded DNA binding; DNA binding; DNA-binding transcription factor activity, RNA polymerase II-specific; RNA polymerase II cis-regulatory region sequence-specific DNA binding; cis-regulatory region sequence-specific DNA binding; DNA-binding transcription activator activity, RNA polymerase II-specific; DNA-binding transcription factor activity; transcription cis-regulatory region binding
Biological process: regulation of transcription by RNA polymerase II; skeletal system development; embryonic hindgut morphogenesis; positive regulation of transcription by RNA polymerase II; prostate gland development; regulation of DNA-templated transcription; response to testosterone
Cellular component: nucleoplasm; chromatin; nucleus
Genetic constraint (gnomAD): Loss-of-function variants: 5 observed, 21.79 expected, observed/expected ratio (o/e) 0.23, 90% interval 0.12 to 0.48. The synonymous counts are far from expectation, so gnomAD's model fits this gene poorly and the ratio says little. Missense variants: 499 observed, 434.44 expected, observed/expected ratio (o/e) 1.15, 90% interval 1.07 to 1.24. Synonymous variants: 244 observed, 195.75 expected, observed/expected ratio (o/e) 1.25, 90% interval 1.12 to 1.39.
Gene-disease validity (ClinGen):
ClinGen rates the evidence that HOXA13 causes each of these diseases.
hand-foot-genital syndrome (autosomal dominant): Definitive. Hand-foot-genital syndrome (HFGS) is a very rare multiple congenital abnormality syndrome characterized by distal limb malformations and urogenital defects.
Homologues: Orthologues: chimpanzee HOXA13 (99% identical), pig HOXA13 (99% identical), dog HOXA13 (99% identical), mouse Hoxa13 (99% identical), rat Hoxa13 (98% identical), macaque HOXA13 (58% identical), rabbit HOXA13 (54% identical), guinea pig HOXA13 (52% identical). Paralogues in human: HOXC13 (43% identical), HOXD13 (41% identical), HOXB13 (39% identical), HOXA11 (19% identical), HOXC11 (19% identical), HOXD11 (17% identical), HOXA10 (16% identical), HOXA4 (15% identical), HOXD10 (14% identical), HOXC12 (14% identical), HOXD4 (14% identical), GSX2 (13% identical), and 30 more.
Diseases named in the same sentence as HOXA13 in open-access papers:
HOXA13 is named in the same sentence as 83 diseases in open-access papers, as found by Europe PMC text mining. Sharing a sentence is not in itself a finding about the gene and the disease. The quoted sentences say what the papers report.
gastric cancer (26 papers, 2012 to 2025). A primary or metastatic malignant neoplasm involving the stomach. "On the other hand, a low expression level of HOXA13 was associated with shorter overall survival of patients with gastric cancer." (PMID 35111675, 2021). "On the other hand, low expression level of HOXA13 was associated with shorter overall survival of patients with gastric cancer." (PMID 35111675, 2021). "Recently, an up-regulation of HOXA13 expression has been associated with highly aggressive forms of gastric cancer, highlighting its prognostic role also in this type of cancer." (PMID 24189220, 2013). "However, the mechanism underlying HoxA13-mediated gastric carcinogenesis and progression of gastric cancer is unclear." (PMID 27144338, 2016). "The lncRNA HOTTIP (HOXA transcript at the distal tip), located near HOXA13, is implicated in the progression of hepatocellular carcinoma (HCC) and gastric cancer by regulating HOXA1345." (PMID 38322121, 2024). "Several documents illustrated the aberrant expression of HOXA13 in a variety of tumors, such as gastric cancer, hepatocellular carcinomas and prostatic neoplasia." (PMID 37392284, 2023). "Some studies suggested that HOTTIP functions as an oncogene by regulating HOXA13 expression in esophageal squamous carcinoma and gastric cancer." (PMID 37392284, 2023). "The expression profile of HOTTIP and HOXA13 was documented as prognostic factor for a variety of cancers, such as pancreatic ductal adenocarcinoma and gastric cancer." (PMID 37392284, 2023). "Differential expression of HOXA13 was also reported in breast cancer, gastric cancer, prostate carcinoma and thyroid cancer." (PMID 32296636, 2020). "However, HOTTIP and HOXA13 have been associated with disease progression and worse outcome in hepatocellular carcinoma, with progression and gemcitabine resistance in pancreatic cancer, and with tumorogenesis and metastasis in esophageal squamous carcinoma and gastric cancer." (PMID 30819158, 2019). "WDR5 has been shown to cooperate with HOTTIP to promote HOXA9 in prostate and pancreatic cancer and HOXA13 expression in esophageal and gastric cancer cells by increasing H3K4Me3 on their promoters." (PMID 29925347, 2018). "HoxA13-HOTTIP-IGFBP-3 cascade is critical for the carcinogenic characteristics in human gastric cancer." (PMID 27806342, 2017). "Similar to our observations, HOXA13 shows enhanced expression in oesophageal squamous cell carcinoma, gastric cancer and hepatocellular carcinoma." (PMID 28402266, 2017). "The identification of differential DNA methylation at the E1 site of the HoxA13 promoter in CSN and CS12 cells is a new finding, which provides a mechanism to explain the upregulation of HoxA13 expression during the development of gastric cancer." (PMID 27144338, 2016). "The expression of HoxA13 was examined by immunohistochemistry (IHC) in gastric cancer obtained from 57 patients." (PMID 27144338, 2016). "HOXA13 and the lncRNA HOTTIP are coregulated in hepatocellular carcinoma, and the lncRNA HOXA11-AS has been implicated in regulating proliferation of several cancers, including gastric cancer." (PMID 38329124, 2024). "Han Y and colleagues demonstrated that HOXA13 expression was elevated in cancerous tissues compared with the corresponding non-cancerous mucosa and expression of HOXA13 was associated with aggressive phenotype of gastric cancer." (PMID 37392284, 2023). "HOXA6 and HOXA13 promote gastric cancer and colorectal cancer." (PMID 37834206, 2023). "HOXA13 is strongly up-regulated in gastric cancer (GC) tissues compared to normal adjacent mucosa." (PMID 31137568, 2019). "We identified both IGFBP-3 and HOTTIP are the target genes of HoxA13 in gastric cancer." (PMID 27144338, 2016). "We also identified the IGFBP-3 as the target of HoxA13 and a positive regulator of gastric cancers." (PMID 27144338, 2016).
gastric cancer (continued). "One previous study reported that increased HoxA13 expression was a poor prognostic factor in gastric cancer, this study further demonstrated that HoxA13 enhanced the migration and invasion ability of gastric cancer cells." (PMID 27144338, 2016). "HoxA13 is a prognostic marker of the aggressive phenotype of gastric cancer." (PMID 27144338, 2016). "In gastric cancer (GC), sustained proliferation is maintained by the activation of the HOXA13-induced Wnt/β-catenin signaling pathway." (PMID 34617205, 2022). "Among these miRNAs, only miR-139-5p was involved in the progression of gastric cancer according to previous reports, which was further verified downregulated in GC cells compared to GES-1 and negatively associated with the expression of HOXA13 in GC tissues in our study." (PMID 34094932, 2021). "Moreover, expression of HoxA13 was observed in gastric cancer specimen." (PMID 27144338, 2016). "In addition, some researcher supposed that HOXA13 was probable to regulate TGF-β signaling by interacting with RUNX3 (runt-related transcription factor 3) mediated by SMADs to promote tumor progression in gastric cancer." (PMID 26356815, 2015). "HOXA13-targeted regulation of CDH17 can affect the Wnt/β-catenin signaling pathway, thus, affecting the progression of gastric cancer." (PMID 35903696, 2022). "Increased expression of HoxA13 (63.2%) and IGFBP-3 (28.6%) was detected in human gastric cancer tissues and was found in the gastric cancer data of The Cancer Genome Atlas." (PMID 27144338, 2016). "We also analyzed HoxA13 and IGFBP-3 expression using the gastric cancer data of The Cancer Genome Atlas and found that both genes were overexpressed." (PMID 27144338, 2016). "By scoring expression levels (0 to 7) by positivity and intensity of IHC staining, HoxA13 and IGFBP-3 were highly expressed (score ≥ 4) in 63.2% (36/57) and 28.6% (8/28), respectively, of these gastric cancer specimens." (PMID 27144338, 2016). "Both HoxA13 and IGFBP-3 were overexpressed significantly in human gastric cancer specimens of Taiwan and The Cancer Genome Atlas." (PMID 27144338, 2016). "For example, the HOXB gene is a prognostic factor in breast cancer 14, HOXA13 expression impaired the chemotherapy in gastric cancer cells 15, HOXB5 promotes metastasis in hepatocellular carcinoma 16 and HOXA13, HOXD13, and HOXC6 were promoted colorectal cancer 17-19." (PMID 37670969, 2023). "We conducted overexpression experiments with gastric cancer cell lines and found that HOXA13 could upregulate CDX2 in SGC-7901 cells but not in MKN-28 cells." (PMID 35999201, 2022). "Similarly, the number of HOXA13-positive cells, but not HOXA13 expression per cell, is increased in IM of the stomach, early gastric cancer, and colorectal cancer." (PMID 34099670, 2021). "Thus, the HoxA13–HOTTIP–IGFBP-3 axis might be an oncogenic pathway in the gastric cancer and a potential new oncotarget for gastric cancer therapy." (PMID 27144338, 2016). "Similar to HOXD13, HOXA13 might be related to the pathogenesis of both poly-Ala tract expansion-related hand-foot-genital syndrome (HFGS) and some types of cancer, such as thyroid and gastric cancers characterized by the aberrant expression of HOXA13, both at gene and protein levels." (PMID 29186753, 2017).
hand-foot-genital syndrome (24 papers, 2007 to 2025). "Although the variable phenotypes were observed in the individuals with HOXD13 heterozygous mutations, the defects were only related to limbs, a single organ system, and seldom syndrome although HOXA13 mutations were associated with hand-foot-genital syndrome." (PMID 34777468, 2021). "The most common amongst these malformations are hand-foot-genital syndrome caused by HOXA13 gene mutation, and synpolydactyly caused by HOXD13 mutation." (PMID 33248450, 2020). "Expansion of this polyA tract in HoxA13 was shown to be a partial cause of the hand-foot-genital syndrome in human." (PMID 26868501, 2016). "Several mutations for posterior genes have been described in HoxA13 (Hand-foot-genital syndrome) and HoxD13 (Synpolydactyly)." (PMID 17845724, 2007). "However, it is critical for the development of the distal limbs and the reproductive system; in fact, HOXA13 mutation is responsible for the rare hand-foot-uterus syndrome (OMIM 140000)." (PMID 26635203, 2015). "Furthermore, hand-foot genital syndrome (caused by HOXA13 mutations) and cleidocranial dysplasia (caused by RUNX2 mutations) may share similar mechanisms." (PMID 40507965, 2025). "In some families with hand-foot-genital syndrome there is a stable expansion of poly-alanine tracts in the GC-rich first exon of the HOXA13 protein." (PMID 34348656, 2021). "The seminal role of HOXA13 in this process has been demonstrated both in knockout mouse models and in patients with hand-foot-genital syndrome (OMIM 14,000)." (PMID 34348656, 2021). "Another interesting disease gene is HOXA13, homeobox A13 (OMIM*142959), causative of the hand-foot-genital syndrome (HFGS, OMIM#140000), which is characterized by small feet with unusually short and big toes and abnormal thumbs, and urogenital malformations." (PMID 31749829, 2019). "Significantly, the 7p15 breakpoint was located 523 kb upstream of HOXA13, the locus for hand-foot-genital syndrome." (PMID 27272187, 2016). "HOXD13/HOXA13/RUNX2 condensates with expanded polyalanine mutation fail to recruit coactivators and disrupt the formation of transcriptionally active TADs, causing synpolydactyly, hand-foot genital syndrome, or cleidocranial dysplasia." (PMID 40507965, 2025). "However, under extremely rare circumstances, homozygosity in pericentric inversion of chromosome 7 may lead to significant disruption in a HOXA13 enhancer sequence and contribute to disease in a patient with hand-foot-genital syndrome." (PMID 40747102, 2025). "For the human HOXA13, in particular, clear associations were established between the expansion of particular polyalanine tracts (I, III and V) and the development of autopod malformations associated with the human hand-foot-genital syndrome (HFGS)." (PMID 29615578, 2016). "While it is known that mutations in HOXA13 or HOXD13 can cause specific limb phenotypes, such as hand-foot-genital-syndrome or synpolydactyly, no HOXA9-related disease phenotype has been identified in patients so far, leaving the role of HOXA9 during human limb development unclear." (PMID 23028966, 2012).
pancreatic cancer (19 papers, 2015 to 2024). "Among the signature genes, HOXA13 is a Homeobox gene overexpressed in multiple cancers and has been shown to be associated with the progression of hepatocellular carcinoma, pancreatic cancer, esophageal squamous cell carcinoma and GBM." (PMID 31531345, 2019). "HOTTIP also determines the pancreatic cancer cells’ resistance to gemcitabine, by overexpression of HOXA13." (PMID 38559560, 2024). "Down-regulation of the HoxA13 protein reduces proliferation, invasion, and chemoresistance of pancreatic cancer cells." (PMID 31137902, 2019). "Li and colleagues found that HOTTIP promotes progression and gemcitabine resistance by regulating HOXA13 in pancreatic cancer." (PMID 31528224, 2019). "Immunohistochemical staining revealed that higher HoxA13 expression was correlated with lymph node metastasis, poor histological differentiation, and decreased overall survival in pancreatic cancer patients." (PMID 31137902, 2019). "HOTTIP is antisense to HOXA13 and modulates cancer stem cell properties in human pancreatic cancer by regulating HOXA9." (PMID 31890219, 2019). "Another study shows that HOTTIP increases pancreatic cancer cell proliferation, survival, and migration through HoxA family genes other than HoxA13." (PMID 27144338, 2016). "In the present study, HOXA13 was the most significantly inhibited gene within the HOXA locus following depletion of HOTTIP in pancreatic cancer cells." (PMID 25889214, 2015). "In addition, HOTTIP expression promotes cancer progression and drug resistance by regulating HoxA13 in pancreatic cancer." (PMID 27144338, 2016). "In addition to the HOTTIP-targeted regulation of HOXA13 expression, we also observed reduced HOTTIP levels upon siRNA-mediated knockdown of HOXA13 in two different pancreatic cancer cell lines." (PMID 25889214, 2015). "HOXA13 is more highly expressed than HOTTIP by over 2 orders of magnitude in all of the pancreatic cancer cell lines; however, despite these differences in the magnitude of expression, there was a correlation between expression of HOTTIP and HOXA13 in most of these cell lines." (PMID 25912306, 2015). "Thus, our work confirms that the regulatory loop between HOTTIP and its target, HOXA13, is also preserved during pancreatic cancer tumorigenesis." (PMID 25889214, 2015). "HOTTIP has been shown to control the proliferation, apoptosis, and migration of pancreatic cancer cells by regulating several HOX genes, including HOXA13, HOXA10, HOXB2, HOXA11, HOXA9, and HOXA1." (PMID 38559560, 2024). "In pancreatic cancer, the long non-coding RNA HOTTIP promotes progression and gemcitabine resistance by regulating HOXA13." (PMID 28881797, 2017). "In pancreatic cancer, the LncRNA HOTTIP promoted gemcitabine resistance through modulating HOXA13." (PMID 32202509, 2020). "In pancreatic cancer, knockdown of lncRNA HOXA transcript at the distal tip (HOTTIP) enhances the chemosensitivity to gemcitabine via consistently modulating HOXA13 level, and overexpression of the HOTTIP/HOXA13 axis indicates poor prognosis and aggressive stage." (PMID 32122355, 2020). "However, another study in pancreatic cancer cells demonstrated that HOTTIP did not modulate HOXA13 expression, but did regulate the expression of other HOX genes such as HOXA1, HOXA9, HOXA10, HOXA11 and HOXB2." (PMID 28938659, 2017). "In pancreatic cancer cells, HOTTIP regulates HOXA10, HOXB2, HOXA11, HOXA9 and HOXA1, but not HOXA13." (PMID 30819158, 2019). "Our results also showed that HOTTIP regulated expression of multiple HOX genes in pancreatic cancer cell cells but, in contrast to results in liver cancer cell lines, HOTTIP did not regulate expression of HOXA13." (PMID 25912306, 2015). "In accordance, we observed that HOTTIP knockdown decreased the expression of several HOXA genes, particularly HOXA11 in a breast cancer-derived cell line, but in contrast to liver cancer cells and consistent with pancreatic cancer cells, HOTTIP does not regulate the expression of HOXA13." (PMID 29415429, 2018).
pancreatic cancer (continued). "Thus, HOTTIP functions in pancreatic cancer cells are due, in part, to regulation of some HOX genes but not HOXA13 as previously observed in liver cancer cells." (PMID 25912306, 2015).